ALOX15B (arachidonate 15-lipoxygenase type B)
Diseases named in the same sentence as ALOX15B in open-access papers (continued):
Sharing a sentence is not in itself a finding about the gene and the disease.
colorectal cancer (4 papers, 2019 to 2023). A primary or metastatic malignant neoplasm that affects the colon or rectum. "ALOX15B (Arachidonate 15-Lipoxygenase Type B) has been demonstrated as risk genes in colorectal cancer and lung squamous cell carcinoma." (PMID 33937273, 2021). "ALOX15B is highly enriched in colorectal cancer tissues in contrast to normal colorectal tissues and is also a poor indicator of patients’ overall survival." (PMID 36836593, 2023). "To confirm whether LXA4-synthesizing enzymes are dysregulated in colorectal cancer, we detected the expressions of ALOX5, ALOX12, ALOX15 and ALOX15B in colorectal cancer tissue." (PMID 31528237, 2019). "Furthermore, the expressions of LXA4-synthesizing enzymes ALOX15 and ALOX15B were down-regulated in colorectal cancer." (PMID 31528237, 2019). "As a result, ALOX5 and ALOX12 were strikingly up-regulated in colorectal polyp, compared with those in colorectal cancer surrounding tissue, while there were no significant change in the expressions of ALOX15 and ALOX15B." (PMID 31528237, 2019).
lung carcinoma (4 papers, 2017 to 2024). "Out of 160 lung carcinomas, ALOX15B was variably expressed in non-small cell lung carcinomas (NSCLC) including 48% of adenocarcinomas and 63% bronchioloalveolar carcinomas." (PMID 38612771, 2024). "Addition of white tea extract (immature, unopened buds of Camellia sinensis) to lung carcinoma A549 cells upregulated ALOX15B expression along with the production of 15-HETE, which led to an upregulation of PPARγ." (PMID 36438817, 2022). "Future research should question if pharmaceutical inhibition of ALOX15B can be targeted in treatments for lung cancers with high ALOX15B expression." (PMID 36438817, 2022). "The distribution of ALOX15B expression in normal lung and lung carcinomas have been reported." (PMID 38612771, 2024). "Thus, the worse prognosis in NSCLC individuals is consistent with the idea that ALOX15B-derived 15(S)-HETE plays a protective role in the course of lung cancer either by activating PPARγ or by downregulating the expression of pro-angiogenic genes." (PMID 28704416, 2017). "The role of ALOX15B in lung cancer biology is poorly characterized." (PMID 28704416, 2017). "The inverse correlation between ALOX15B levels and lung cancer grade can be explained by the fact that 15(S)-HETE can bind and activate PPARγ, a nuclear transcription factor shown to inhibit the growth of human NSCLC cells as well as prevent smoking-induced lung cancer development in mice." (PMID 28704416, 2017). "Likewise, ALOX15B expression was also increased under hypoxic conditions in cardiac fibroblasts, pulmonary artery smooth muscle and endothelial cells, as well as lung cancer cell line A549." (PMID 36438817, 2022).
atopic dermatitis (3 papers, 2018 to 2024). "Some of lipid metabolic genes discovered in our analysis were also reported as declined genes in patients with psoriatic (ACSBG1, ALOX15B, ELOVL3, FADS1, FADS2, and THRSP) or atopic dermatitis (CYP4F8, ELOVL3, FADS1, FADS2, FAR2, and HAO2)." (PMID 30021930, 2018).
coronary artery disease (3 papers, 2016 to 2022). "In line, data of a case-control study indicated the association of distinct ALOX15B gene polymorphisms with coronary artery disease and patients diagnosed with stroke were found to have high expression of ALOX15B." (PMID 36438817, 2022). "The increased expression of ALOX15 mRNA in ischemic heart disease is in agreement with our earlier results but we had not previously investigated ALOX15B or ALOX12 expression in ischemic heart tissue." (PMID 27552229, 2016). "In this study, we showed that expression of ALOX15 (but not ALOX15B or ALOX12) and 15-HETE levels were substantially higher in myocardial tissue from patients undergoing heart surgery for ischemic heart disease compared with myocardial tissue from those undergoing AVR surgery." (PMID 27552229, 2016).
ischemic stroke (3 papers, 2014 to 2020). A stroke disorder caused by obstruction of blood flow to the brain, due to thrombotic (local blood clot formation) or embolic (due to a blood clot or other material traveling from another site) event. "However, a recent biomarker study found increased HETE levels in the plasma of ischemic stroke patients, suggesting that ALOX15B products may play a role in thrombosis." (PMID 24533104, 2014). "We have previously shown that ALOX15B is expressed in macrophage-rich regions, and here we extended these findings to demonstrate that ALOX15B is higher in carotid plaques with thrombosis versus no thrombosis and in plaques from patients who had suffered an ischemic stroke compared with TIA." (PMID 24533104, 2014).
asthma (2 papers, 2018 to 2022). "The contrasting ALOX15B expression levels between asthma and cystic fibrosis may be explained by the vastly different pathologies of these diseases." (PMID 36438817, 2022). "Indeed, both diseases have dysregulated airway epithelium, however, the increased Th2 cytokines in asthma could have potentially upregulated ALOX15B in both macrophages and airway epithelial cells." (PMID 36438817, 2022). "Since our data links macrophage ALOX15B to CCL17 production and T cell migration, we reasoned whether these findings might be relevant to human asthma." (PMID 30197642, 2018).
cystic fibrosis (2 papers, 2022 to 2024). Autosomal recessive disorder caused by pathogenic variants in the CFTR gene (cystic fibrosis transmembrane conductance regulator), which encodes a chloride and bicarbonate channel expressed in epithelial cells, and follow the diagnosis criteria. "In contrast, cystic fibrosis showed decreased ALOX15B expression, and chronic obstructive pulmonary disease reduced levels of 15-HETE." (PMID 38637408, 2024). "In contrast, cystic fibrosis patients showed a significant decrease in ALOX15B in macrophages and neutrophils of bronchoalveolar lavage." (PMID 36438817, 2022). "Furthermore, cells with F508del CFTR [a phenylalanine deletion common in cystic fibrosis patients] demonstrated a further reduction of ALOX15B expression when compared to the WT CFTR expression in CFBE41o− bronchial epithelial cells." (PMID 36438817, 2022). "Moreover, the authors suggested that reduced ALOX15B expression may be due to the cystic fibrosis gene CF transmembrane conductance regulator (CFTR), impairing macrophage function." (PMID 36438817, 2022).
depression (2 papers, 2023 to 2025). "Then, we measured the concentrations of ALOX15B (also known as Alox8 in mice), RPLP0 and HP in our depression mouse model." (PMID 37942417, 2023). "Furthermore, ferroptosis-related genes, such as ALOX15B (Arachidonate-15-Lipoxygenase, Type B) and RPLP0 (ribosomal protein lateral stalk subunit P0), have been identified as potential biomarkers for diagnosing depression." (PMID 40177374, 2025).
glioma (2 papers, 2022). A benign or malignant brain and spinal cord tumor that arises from glial cells (astrocytes, oligodendrocytes, ependymal cells). "The Macro index comprised of PIK3R5, PIK3R6, ALOX5, ALOX5AP, and ALOX15B serves as a valid prognostic biomarker for gliomas, especially LGG." (PMID 36159811, 2022).
heart failure (2 papers, 2018 to 2024). Inability of the heart to pump blood at an adequate rate to meet tissue metabolic requirements. "In the present study, we demonstrate for the first time that ALOX15 and ALOX15B is expressed in failing human hearts, and that ALOX15/B signaling therefore may contribute to human heart failure." (PMID 30138423, 2018).
ovarian carcinoma (2 papers, 2022). A malignant neoplasm originating from the surface ovarian epithelium. "During development of ovarian cancer, expression of ALOX15B is strongly augmented and high levels of ALOX15B mRNA have also been detected in metastatic tissue." (PMID 35740398, 2022). "Since mouse Alox15b exhibits a different reaction specificity than its human ortholog, it remains unclear whether mouse Alox15b fulfils similar functions in mouse models of prostate and/or ovarian cancer." (PMID 35740398, 2022).
prostate tumor (2 papers, 2009 to 2012). "The gene ALOX15B is a suppressor of prostate tumor development and in this data set is down-regulated in tumors of high-grade and in tumors that recurred." (PMID 19356222, 2009).
Stroke (2 papers, 2014 to 2022). Sudden impairment of blood flow to a part of the brain due to occlusion or rupture of an artery to the brain. "The present study showed that ALOX15B expression in human carotid plaques was associated with thrombus formation in the plaque, and high expression of ALOX15B was found in patients diagnosed with stroke." (PMID 24533104, 2014). "Furthermore, ALOX15B staining was higher in plaques from patients diagnosed with stroke than in patients diagnosed with TIA." (PMID 24533104, 2014). "Interestingly, ALOX15B mRNA levels were described to be higher in symptomatic plaques with attributable cerebrovascular symptoms (amaurosis fugax, transient ischemic attack, or stroke) than in asymptomatic plaques." (PMID 36438817, 2022).
Alzheimer disease (1 paper, 2014). A progressive, neurodegenerative disease characterized by loss of function and death of nerve cells in several areas of the brain leading to loss of cognitive function such as memory and language. "mRNA and protein levels of cPLA2 IVA (PLA2G4A), sPLA2 IIA (PLA2G2A), COX-1 and -2 (PTGS1, PTGS2), mPGES1 (PTGES1), and LOX-12 and -15 (ALOX12B, ALOX15B), are increased in Alzheimer's disease in the frontal cortex, hippocampus, and cerebellum." (PMID 24963629, 2014).
breast tumors (1 paper, 2022). "Also, ALOX15B expression was negatively correlated with breast tumor stage and a low ALOX15:ALOX15B ratio was associated with a poorer prognosis, yet amplification of ALOX15B had a negative effect on survival." (PMID 36438817, 2022). "Intriguingly, ER expression inversely correlated with ALOX15B expression in normal breast tissue, however ER positive breast tumors had a higher ALOX15B expression than ER negative tumor." (PMID 36438817, 2022).
colitis (1 paper, 2023). Inflammation of the colon. "Since the higher susceptibility of Alox15b-KI mice in the DSS–colitis model might be related to a different profile of pro- and/or anti-inflammatory eicosanoids, we next employed a lipidomic approach and quantified the steady state concentrations of 44 different eicosanoids in the colon tissue." (PMID 37446212, 2023). "Humanization of the reaction specificity of mouse Alox15b (Alox8) sensitizes mice for dextran sodium sulfate-induced experimental colitis, while it partly protected the animals in the complete Freund’s adjuvant-induced paw edema model." (PMID 37446212, 2023). "Here, we tested young Alox15b-KI mice in two different whole-animal inflammation models and found that Alox15b-KI mice lost significantly more bodyweight during the acute phase of dextran sodium sulfate (DSS)-induced colitis than outbred wildtype controls." (PMID 37446212, 2023). "Since humanization of the reaction specificity of Alox15b might impact the biosynthetic capacity of this enzyme for pro- and/or anti-inflammatory eicosanoids, we tested the susceptibility of the Alox15b-KI mice and outbred wildtype controls in the DSS–colitis model." (PMID 37446212, 2023).
colorectal adenocarcinoma (1 paper, 2022). The most common type of colorectal carcinoma. "Data on 594 colorectal adenocarcinoma revealed that FPR1 mRNA levels significantly and directly correlated with mRNA expression levels of the proresolving factors ALOX5 and ALOX15B." (PMID 35808840, 2022).
colorectal polyp (1 paper, 2019). "Furthermore, we detected the expressions of ALOX5, ALOX12, ALOX15 and ALOX15B in colorectal polyp." (PMID 31528237, 2019).
esophageal cancer (1 paper, 2024). A primary or metastatic malignant neoplasm involving the esophagus. "Expression of ALOX15B mRNA and protein is lost in esophageal cancers and upregulation of ALOX15B during a COX-2 inhibitor, NS398, treatment is associated with reduced cancer cell survival and proliferation." (PMID 38612771, 2024).
head and neck carcinoma (1 paper, 2024). A carcinoma that arises from the head and neck region. "This upregulation of ALOX15B led to increased apoptosis enhancing the impact of radiotherapy in head and neck cancers." (PMID 38612771, 2024). "It is already known that ALOX15B is significantly downregulated in head and neck carcinoma." (PMID 38612771, 2024).
influenza infection (1 paper, 2022). "Male Alox15b knockout mice show impaired recovery from influenza infection when compared with wildtype littermates." (PMID 35740398, 2022).
ischemia (1 paper, 2014). A hypoperfusion of the BLOOD through an organ or tissue caused by a PATHOLOGIC CONSTRICTION or obstruction of its BLOOD VESSELS, or an absence of BLOOD CIRCULATION. "Here we show that neither ischemia nor ALOX15B knockdown affected tissue factor levels in macrophage lysates, indicating that tissue factor does not explain the changes in platelet aggregation and thrombin generation observed in our macrophage experiments." (PMID 24533104, 2014).
lung adenocarcinoma (1 paper, 2022). A carcinoma that arises from the lung and is characterized by the presence of malignant glandular epithelial cells. "Yet in lung adenocarcinoma A549 cells, ALOX15B expression and 15-HETE production has been induced under hypoxia." (PMID 36438817, 2022). "Evidence in A549 cells suggested that ALOX15B promotes proliferation through 15-HETE in lung adenocarcinomas." (PMID 36438817, 2022).
lymphoma (1 paper, 2023). A malignant (clonal) proliferation of B- lymphocytes or T- lymphocytes which involves the lymph nodes, bone marrow and/or extranodal sites. "ALOX15B deficiency leads to accumulation of its substrate, arachidonic acid (AA), and accelerates Myc-driven lymphoma." (PMID 36750552, 2023). "We showed that ALOX15B deficiency with chromosome 17p deletions was demonstrated to promote lymphomagenesis and maintain corresponding lymphoma cell growth through upregulating COX-2 level." (PMID 36750552, 2023). "In this study, we profiled the metabolites derived from AA in del(17p) and ALOX15B deficient lymphoma cells by liquid chromatography-mass spectrometry (LC-MS)." (PMID 36750552, 2023). "In contrast, ALOX15B is recognized to have an anti-carcinogenic effect as its downregulated expression in various cancers and its loss driving lymphoma development." (PMID 36750552, 2023). "ALOX15B and ALOX12 in lymphoma have been reported to have a tumor-suppressive role in promoting murine lymphomas, while ALOX5, the only one not on chromosome 17p, seems to be required at least for some types of leukemia." (PMID 36750552, 2023).
pituitary adenomas (1 paper, 2024). "In the pathogenesis of pituitary adenomas, the expression of both ALOX15 and ALOX15B as well as their metabolites 15-(S)-HETE, 13-(S)-HODE are significantly elevated respectively." (PMID 38612771, 2024). "In the pathogenesis of pituitary adenomas, the expression of both ALOX15 and ALOX15B as well as their metabolites 15-(S)-HETE, 13-(S)-HODE are significantly elevated." (PMID 38612771, 2024).
rheumatoid arthritis (1 paper, 2022). A chronic, systemic autoimmune disorder characterized by inflammation in the synovial membranes and articular surfaces. "Therefore, ALOX15B expression in human macrophages or tissues associated with rheumatoid arthritis still needs to be determined." (PMID 36438817, 2022).
Splenomegaly (1 paper, 2022). Abnormal increased size of the spleen. "If this is the case for Alox15b-KI mice, the in vivo life span of peripheral red blood cells should be reduced, which frequently induces reticulocytosis and splenomegaly." (PMID 35740398, 2022). "To explore whether Alox15b-KI mice suffer from splenomegaly, we compared the spleen weights of middle-aged (30–40 weeks) Alox15-KI mice and outbred wildtype controls but did not detect significant differences between the two genotypes." (PMID 35740398, 2022).
thrombosis (1 paper, 2014). "Examination of the 120 human carotid plaques showed that the extent of ALOX15B staining correlated with staining for the macrophage marker CD68 (rs = 0.45, P<0.0001), as expected, and was higher in carotid plaques with thrombosis compared with no thrombosis." (PMID 24533104, 2014).